STAT1 (signal transducer and activator of transcription 1)
Diseases named in the same sentence as STAT1 in open-access papers (continued):
Sharing a sentence is not in itself a finding about the gene and the disease.
pouchitis (1 paper, 2020). Acute inflammation in the intestinal mucosa of the continent ileal reservoir (or pouch) in patients who have undergone ileostomy and restorative proctocolectomy (proctocolectomy, restorative). "Furthermore, there was a tendency towards increased levels of IFN-γ and STAT1 in patients with UC, even without clinical and endoscopic evidence of pouchitis." (PMID 32811425, 2020).
prediabetes (1 paper, 2023). "Similarly, the IFN-γ/STAT-1 axis also regulates the tolerogenic activity of IDO in dendritic cells in a mouse model of prediabetes." (PMID 37334380, 2023).
prostatic neoplasms (1 paper, 2012). "Moreover, 3 genes STAT1, ERBB3, P21 (CDKN1A) were found to be associated with ‘prostatic neoplasms regulation of progression through cell cycle’ and 1 gene STAT1 is associated with ‘prostatic neoplasms inflammatory response’." (PMID 22870216, 2012).
prostatitis (1 paper, 2017). An infectious or non-infectious inflammatory process affecting the prostate gland. "IFN-γ/STAT1 signaling pathway has also been shown plays an important role in the immune responses to prostatitis in experimental autoimmune prostatitis mouse model." (PMID 28665978, 2017). "In this study we investigated whether the testosterone reduces the prostatitis and related mechanism by regulating IFN-γ/STAT1 signaling pathway." (PMID 28665978, 2017). "However the researches about whether the testosterone reduces the prostatitis and the regulated mechanism relate to IFN-γ/STAT1 signaling pathway both remain lacked." (PMID 28665978, 2017).
pulmonary mycobacterial infection (1 paper, 2019). "It has been reported that low levels of anti-IFN-γ autoAbs were found in plasma from healthy controls and patients with pulmonary mycobacterial infection but that these autoAbs were not biologically active in terms of inhibiting STAT-1 phosphorylation." (PMID 31474987, 2019).
pulpitis (1 paper, 2021). Inflammation of the dental pulp. "Several transcription factors have been identified to be involved in the TF-gene regulatory network of pulpitis, including GATA2, ETS1, FOXP3, STAT1, FOS, and JUN." (PMID 33777260, 2021). "Six transcription factors (i.e., GATA2, ETS1, FOXP3, STAT1, FOS, and JUN) were identified to play pivotal roles in pulpitis." (PMID 33777260, 2021).
respiratory allergy (1 paper, 2021). "According to the individual score, neither AKT1, MAPK13, nor STAT1 presented a high probability of promoting respiratory allergy on their own." (PMID 33936056, 2021).
retinal vein occlusion (1 paper, 2023). An occlusion of the retinal vein. "Proteins that were upregulated in our study and in experimental retinal vein occlusion included fibronectin, annexin A1, galectin-3, alpha-crystallin B chain, vimentin, annexin A2, STAT1, GFAP, osteopontin, vitronectin, and clusterin." (PMID 37175625, 2023).
retinoblastoma (1 paper, 2025). A malignant tumor that originates in the nuclear layer of the retina. "By regulating miR-99a expression and reducing the phosphorylation of JAK1, STAT1, and STAT3, curcumin drives apoptotic cell death in retinoblastoma cells." (PMID 41020838, 2025). "Similarly, in retinoblastoma cells, curcumin downregulates JAK1 and STAT1/STAT3 phosphorylation while modulating miR-99a, which mechanistically leads to apoptotic cell death." (PMID 41020838, 2025).
rhabdoid tumor (1 paper, 2013). An aggressive malignant embryonal neoplasm usually occurring during childhood. "In human pediatric rhabdoid tumor G401 cells, midkine activates the anti-apoptotic pathway mediated by STAT1 and the Janus-activated kinases (JAKs)." (PMID 24083030, 2013).
rickettsia infections (1 paper, 2024). "Our previously published work clearly demonstrated that rickettsia infections of ECs activate NF-κB and STAT-1/3 and increase the secretion of cytokines and chemokines." (PMID 38399700, 2024).
ROSAH syndrome (1 paper, 2025). "In line with this hypothesis, increased expression of interferon-regulated genes and phosphorylation of STAT1 have been described in patients with ROSAH syndrome." (PMID 39868044, 2025).
scrub typhus (1 paper, 2024). Scrub typhus is a rare dust mite-borne infectious disease caused by the Orientia tsutsugamushi bacterium and characterized clinically by an eruptive fever which is potentially serious. "Using double Ifnar1-/-Ifngr1-/- and Stat1-/- mice, we found that deficiency in IFN/STAT1 signaling resulted in lethal infection with profound pathology and skin eschar lesions, which resembled to human scrub typhus." (PMID 38743761, 2024). "In contrast, both double Ifnar1-/-Ifngr1-/- and Stat1-/- mice displayed evident skin lesions marked by necrosis of the overlying epidermis and hardening features, surrounded by an indurated red halo (red arrows), which resembled skin eschars in scrub typhus patients." (PMID 38743761, 2024).
seminoma (1 paper, 2025). A radiosensitive malignant germ cell tumor found in the testis (especially undescended), and extragonadal sites (anterior mediastinum and pineal gland). "The molecular distinction between seminomas and teratomas enables tailored therapeutic approaches: in seminomas, synthetic hsa-miR-138-5p mimics could reinforce apoptotic and anti-inflammatory pathways, while PD-1/PD-L1 checkpoint inhibitors may overcome STAT1- and CD8A-driven immune escape." (PMID 40869426, 2025).
sensorineural hearing loss (1 paper, 2021). "Immunocompromised STAT-1-/- mice provide a valuable model to study LASV-induced pathology during late stages of the recovery, which include sensorineural hearing loss, SHL." (PMID 33573250, 2021).
serous carcinoma (1 paper, 2018). "The positive staining of total STAT1 was observed in all high-grade serous carcinoma (n = 5)." (PMID 29751820, 2018). "However, when we compared the grade of serous carcinoma, a main type of EOC, we found that the total STAT1 but not the phospho-forms was significantly different between high-grade and low-grade serous carcinoma (P = 0.031)." (PMID 29751820, 2018).
Shock (1 paper, 2022). The state in which profound and widespread reduction of effective tissue perfusion leads first to reversible, and then if prolonged, to irreversible cellular injury. "Moreover, PFIE suppressed the phosphorylation and nuclear translocation of STAT1 in LPS-stimulated J774 cells, suggesting that PFIE can inhibit LPS- and CLP-induced septic shock by suppressing the STAT1 activation." (PMID 36185646, 2022).
silicosis (1 paper, 2024). Silicosis is a respiratory disease caused by breathing in (inhaling) silica dust. "Modulating the acetylation level of STAT1 with geranylgeranylacetone effectively inhibited the progression of silicosis." (PMID 38641226, 2024). "Taken together, these data indicate that GGA can attenuate the progression of silicosis in mice through interfering posttranslational acetylation of Stat1." (PMID 38641226, 2024). "•Identification of STAT1 acetylation as a therapeutic target for silicosis." (PMID 38641226, 2024). "Co-immunoprecipitation was carried out to investigate Stat1, which may play a significant role in silicosis mechanisms." (PMID 38641226, 2024). "Furthermore, we confirmed STAT1 acetylation as a novel therapeutic target of silicosis and the results supported the potency of targeting STAT1 acetylation by geranylgeranylacetone in the treatment of silicosis." (PMID 38641226, 2024). "STAT1, classically regarded as regulator of IFN/STAT signaling in silicosis, can be acetylated and succinylated with significant adjustments on its activity and function, while the influence of these PTM alterations in pulmonary fibrotic diseases remains unclear." (PMID 38641226, 2024).
Skin rash (1 paper, 2016). A red eruption of the skin. "When the STAT1-blind recombinant virus was assessed for virulence in rhesus monkeys, none of the monkeys infected with the STAT1-blind strain developed skin rash, anorexia or diarrhoea seen with wt virus." (PMID 27367734, 2016).
skin squamous cell carcinoma (1 paper, 2022). A carcinoma arising from the squamous cells of the epidermis. "Tissue microarray analysis of human skin squamous cell carcinoma (SCC) also showed enrichment of STAT1 in the invasive front of SCCs." (PMID 35606369, 2022).
spinal cord injury (1 paper, 2021). Penetrating and non-penetrating injuries to the spinal cord resulting from traumatic external forces (e.g., WOUNDS, GUNSHOT; WHIPLASH INJURIES; etc.). "Valproic acid treatment inhibited HDAC3 expression and activity, enhanced STAT1, and acetylated NF-κB p65 after spinal cord injury (SCI)." (PMID 34764819, 2021).
spondylitis (1 paper, 2018). The inflammation of a vertebra. "STAT1 expression was reported to be significantly higher in RA synovial tissue than in OA and mandatory spondylitis." (PMID 30286793, 2018).
Still’s disease (1 paper, 2021). "In contrast, tocilizumab, through the collateral modulation of STAT1, preferably modulates FCGR1 activity, which is involved in neutrophil activation, a relevant hallmark in Still’s disease." (PMID 33892792, 2021).
synovial sarcoma (1 paper, 2024). "Collectively, these results point to a potential involvement for FAM83D in the development of synovial sarcoma could be mediated via the regulation of STAT1, BIRC5, MCM2, as well as CDK1." (PMID 38512482, 2024). "Investigations into the molecular mechanisms underpinning FAM83D’s regulation of STAT1, BIRC5, MCM2, as well as CDK1 in synovial sarcoma, are currently underway in our laboratory." (PMID 38512482, 2024).
Thrombocytosis (1 paper, 2024). Increased numbers of platelets in the peripheral blood. "The ablation of Stat3 resulted in an altered JAK2 V617F phenotype, with decreased neutrophilia, although thrombocytosis was enhanced, while the ablation of Stat1 actually exacerbated JAK2 V617F-induced erythrocytosis in a mouse model despite reducing the thrombocytosis." (PMID 38254802, 2024).
thyroid tumor (1 paper, 2015). A benign or malignant neoplasm affecting the thyroid gland. "Similar to BC, adjusting ADAR expression for ADAR copy number increased the correlation between ADAR and STAT1 for all except pancreatic, kidney, and thyroid tumors." (PMID 26440892, 2015).
toxocariasis (1 paper, 2019). A parasitic infection caused by worms found in domestic animals. "To better understand the possible roles played by M1 and M2 macrophages during acute toxocariasis, we used STAT1- or STAT6-deficient mice." (PMID 31810203, 2019). "Collectively, these data suggest that STAT6 deficiency promotes M1 macrophage activation and lung tissue damage, while the absence of STAT1 is associated with M2 macrophage polarization and early lung tissue repair during acute toxocariasis." (PMID 31810203, 2019).
trachoma (1 paper, 2017). "STAT1 and STAT4 have previously been shown to be associated with active trachoma and ocular C. trachomatis infection, and STAT1 was upregulated in cervical epithelial cells infected with C. trachomatis in vitro which was found to inhibit chlamydial growth." (PMID 28966918, 2017).
tularemia (1 paper, 2019). Tularemia is an infection caused by the bacterium Francisella tularensis. "Changes in gene expression, including upregulation of STAT1, GBP1, and IFIT2, predicted tularemia-specific antibody responses." (PMID 31878161, 2019).
uterine cancer (1 paper, 2024). Primary or metastatic malignant neoplasm involving the uterine corpus and/or the cervix. "Multivariable analysis showed an independent association between high IDO1 and high PD-L1, high CXCL10, high STAT1, and between high IDO1 and ovarian and uterine cancers; tumors in men were significantly associated with lower IDO1 levels (all multivariable p values <0.05)." (PMID 38632994, 2024).
uterine infection (1 paper, 2022). "When comparing all four studies, a total of 24 genes were consistently upregulated by pregnancy regardless of previous uterine infection, including DKK1, MX1, MX2, STAT1 and a number of interferon stimulated genes." (PMID 35358206, 2022).
vascular dementia (1 paper, 2022). A degenerative vascular disorder affecting the brain. "The inhibition of JAK/STAT1-mediated neuroinflammation alleviated learning and memory impairment, and improved synaptic protein expression in an animal model of vascular dementia." (PMID 36499161, 2022).
Vertigo (1 paper, 2022). An abnormal sensation of spinning while the body is actually stationary. "To substantiate the circ_0000811/miR-15b/Prkar2a/JAK2/STAT1 regulatory axis in vivo, we performed a series of gain- and loss- of functions assays on mice with experimental CI-induced vertigo." (PMID 35508616, 2022). "Circ_0000811 sponged miR-15b to inhibit its expression and augment Prkar2a expression, whereby the JAK2/STAT1 signaling pathway was repressed, and the apoptosis of neurons was thus attenuated to mitigate the CI-induced vertigo." (PMID 35508616, 2022). "Taken together, the data acquired in the present study elucidated the mechanism by which circ_0000811 overexpression ameliorated CI-induced vertigo through attenuating the apoptosis of neurons via the modulation of the miR-15b/Prkar2a/JAK2/STAT1 cascade." (PMID 35508616, 2022). "First, we observed that the phosphorylation levels of JAK2 and STAT1 were increased in the MVN of mice with CI-induced vertigo as well as in OGD-exposed cells." (PMID 35508616, 2022). "Furthermore, our data revealed that Prkar2a inactivated the JAK2/STAT1 signaling pathway, thus attenuating neuronal apoptosis in CI-related vertigo." (PMID 35508616, 2022). "The results unraveled that the AG490-induced inhibition of the JAK2/STAT1 signaling pathway alleviated CI-induced vertigo through repression of neuronal apoptosis, its combination with circ_0000811 strengthening the effects of circ_0000811 overexpression alone." (PMID 35508616, 2022). "Hence, circ_0000811 may mitigate CI-induced vertigo through suppressing the JAK2/STAT1 signaling pathway to attenuate neuronal apoptosis." (PMID 35508616, 2022). "Furthermore, inactivation of the JAK2/STAT1 signaling pathway exerted an anti-apoptotic effect in OGD-induced neurons and an alleviatory effect in mice with CI-induced vertigo with Prkar2a overexpression and circ_0000811 overexpression." (PMID 35508616, 2022).
Werner syndrome (1 paper, 2018). "We show that unphosphorylated STAT1 and STAT2 protein levels are increased in NHDFs after in vitro cellular aging as well as in fibroblasts from a patient with Werner syndrome, which leads to premature aging." (PMID 30455980, 2018). "Therefore, the increased ISG expression in cells from a patient with Werner syndrome may be independent of phosphorylated STAT1 and STAT2, similar to the case in senescent NHDFs." (PMID 30455980, 2018).
Zinc deficiency (1 paper, 2020). A deficiency of the essential metal Zinc; an essential cofactor for many enzymes. "In the central nervous system (CNS), zinc deficiency has been demonstrated to disrupt STAT1 signalling in the development of the foetal CNS." (PMID 33153045, 2020). "Zinc deficiency also results in oxidative stress in embryonic and brain cells through compromised tyrosine phosphorylation of STAT1." (PMID 33153045, 2020). "A study has shown that zinc chelation decreased STAT1 upregulation in macrophages and this may be relevant to elderly people suffering from a higher risk of bacterial infection because of zinc deficiency." (PMID 33153045, 2020).
tumor (1,433 papers, 2003 to 2026). "MCL-1 inhibition downregulates MYC and activates the STAT1-interferon inflammatory pathway, promoting cytotoxic T-cell infiltration with reduced tumor-associated myeloid cells both in vitro and in vivo." (PMID 41680300, 2026). "Meanwhile, DDR1 has been implicated in tumor cell dormancy across various experimental models by upregulating type III collagen via STAT1 activation." (PMID 41492134, 2026). "Mechanically, we identified that STAT1 was associated with tumor resistance and N2 neutrophil polarization during ICIs treatment." (PMID 40226609, 2025). "Specifically, Ptdss1-deficient tumor cells were more responsive to IFN-γ stimulation through the STAT1 signaling pathway, resulting in greater MHC-I surface expression, and, ultimately, enhanced CD8+ T cell–mediated cell killing in vitro." (PMID 40929270, 2025). "In order to delve deeper into the underlying mechanism, we examined the connection between STAT1 and tumor-infiltrating cells." (PMID 40226609, 2025). "The transcription factor STAT1 can regulate associated genes to limit tumor development and metastasis." (PMID 40659662, 2025). "STAT1, a key molecule in signal transduction within the tumor microenvironment, is intimately associated with inflammatory responses and tumor immune surveillance." (PMID 40406250, 2025). "IL-18 deficiency due to NLRP3 loss can impair IFN-γ production as well as STAT1 activation, thereby increasing tumor burdens in CRC." (PMID 41291696, 2025). "In our study, we observed a significant decrease in NF-κB (p65) protein levels in tumor cells expressing the STAT1-∆N mutation compared with their WT counterparts." (PMID 40287766, 2025). "Based on recent studies, SP140 enhances STAT1 signaling in tumor-associated macrophages, which subsequently increases the expression of PD-L1." (PMID 41188771, 2025). "CircPIAS1 (circbase ID: hsa_circ_0008378) and its encoded protein circPIAS1-108aa contribute to tumor progression by suppressing STAT1 phosphorylation and immunogenic ferroptosis, yet specific pharmacological agents of directly targeting circPIAS1 are lacking." (PMID 41347180, 2025). "Studies have demonstrated that P4HA2 governs the expression of STAT1, which, as a crucial molecule of signal transduction within the tumor microenvironment, is intimately associated with the inflammatory response and tumor immune surveillance." (PMID 40406250, 2025). "Together, the findings revealed that Hmgb2 deficiency–induced tumor regression depended on STAT1/CXCL10/CXCR3 pathway." (PMID 40315321, 2025). "Tumor-associated macrophages further amplify C5a production through platelet-mediated activation of the JNK/STAT1 pathway, promoting tumor growth." (PMID 41031883, 2025). "Studies revealed that tumor growth rate and IFN-γ-driven tumor cell killing by NK and T cells were accelerated in STAT1 knockout mice, suggesting that loss of STAT1 negatively affects both innate and adaptive anti-tumor responses." (PMID 39136000, 2024). "Particularly, STAT1 has a close association with the development of advanced tumors and the maintenance of stem cells in terms of anti-tumor function." (PMID 39208654, 2024). "The significant overexpression of STAT1 indicates that fludarabine’s tumor selectivity is associated with its regulatory influence on inhibiting STAT1 function and malignant metabolic activity, and it is clinically relevant." (PMID 39518046, 2024). "In this study, we examined the role of STAT1−/− in promoting the natural course of histopathological tumor progression in HPV-associated cancers." (PMID 38675812, 2024). "By implementing SCENIC, we found nine tumor–associated GRNs within the PtR and PtRP GEMMs including one defined by Stat1/2 and Irf2/7/9, validating our recent findings on the critical role of JAK/STAT signaling in initiating plasticity." (PMID 38645034, 2024). "On the one hand, STAT1 activation has been linked to enhanced tumor resistance against chemotherapy, immunotherapy, and radiotherapy." (PMID 38675812, 2024).